LYVE1 (lymphatic vessel endothelial hyaluronan receptor 1)
Diseases named in the same sentence as LYVE1 in open-access papers (continued):
Sharing a sentence is not in itself a finding about the gene and the disease.
infection (continued). "Infection also led to a reduction in LYVE1 abundance, but little or no change in CD180 or CD206 abundance, in macrophages." (PMID 37318981, 2023). "A similar result was also observed in mice pre-treated with LYVE-1 mAb following infection with M89 GAS, confirming the same key role for LYVE-1 in the translocation of encapsulated GAS to draining lymph nodes indicated from the studies carried out with LYVE-1-/- mice." (PMID 26352587, 2015). "Despite the altered expression and spatial distribution of Lyve1 expression observed by confocal microscopy, total LEC, medullary, and floor LEC numbers remained similar in LNs from mock-, CHIKV 181/25–, and WT CHIKV–infected mice at 48 hours after infection when evaluated by flow cytometry." (PMID 38194268, 2024). "Further comparative analyses between Lyve1+ and Lyve1− macrophages within the dura mater revealed that the expression of multiple MHC class II molecules was enriched in the latter, suggesting the specialized immune-surveillance role of these cells in dura mater protection against infection." (PMID 32737287, 2020). "We confirmed that the Lgy parasites were mostly located in Lyve1+ lymphatic sinus space, both in the SCS and MS of each infected LN, while the CD31+ blood vessels showed a meager-to-no mCherry+ co-localization at this point of infection." (PMID 36034709, 2022).
kidney disease (1 paper, 2026). "This study investigates alterations in LYVE1 during kidney disease and elucidates its role in macrophage trafficking." (PMID 41587141, 2026).
LYVE1 also shares sentences with these, for which no sentence is quoted: COVID-19 (4 papers); glioblastoma (4); neurodegenerative disease (3); renal carcinoma (3); cognitive disorder (2); dilated cardiomyopathy (2); inflammation (2); ischemic stroke (2); Kaposi's sarcoma (2); triple-negative breast carcinoma (2); acute myocardial infarction (1); adenoma (1); amyloidosis (1); Atrophy (1); Autoimmunity (1); benign ovarian tumors (1); capillary malformation (1); cardiomyopathy (1); childhood asthma (1); chronic pancreatitis (1); Chylothorax (1); ciliary body melanoma (1); cortical atrophy (1); cyst (1); cystic fibrosis (1); developmental delay (1); diabetic neuropathy (1); diffuse large B-cell lymphoma (1); Epiretinal membrane (1); esophageal adenocarcinoma (1).
A further 48 diseases each share a sentence with LYVE1 in 1 paper.